Y_RNA (Y RNA )
Gene: Miscellaneous RNA gene on chromosome 20 (44,344,839 to 44,344,933, forward strand). Ensembl gene ENSG00000201363.
Homologues: Orthologues: chimpanzee Y_RNA (92% identical). Paralogues in human: RNY1 (82% identical), Y_RNA (81% identical), Y_RNA (80% identical), RNY1P5 (79% identical), Y_RNA (79% identical), RNY1P2 (78% identical), RNY1P8 (78% identical), Y_RNA (78% identical), RNY1P11 (77% identical), RNY1P7 (77% identical), Y_RNA (77% identical), Y_RNA (76% identical), and 87 more.